PPARG (peroxisome proliferator activated receptor gamma)
Diseases named in the same sentence as PPARG in open-access papers (continued):
Sharing a sentence is not in itself a finding about the gene and the disease.
infection (continued). "SARS-CoV-2 infection of human primary monocytes up-regulated the pathways involved in lipid uptake such as CD36, the major transcriptional factors involved in lipogenesis, PPARγ and SREBP-1, and the enzyme DGAT-1, which is involved in triacylglycerol synthesis, after 24 hours of infection." (PMID 33326472, 2020). "In a prior experiment, treatment of goats with the putative PPARγ agonist 2,4-thiazolidinedione (2,4-TZD) ameliorated the response to intramammary infection without evidence of PPARγ activation." (PMID 31195666, 2019). "Infection of macrophages with Mycobacterium bovis bacillus Calmette-Gue ́rin (BCG) resulted in lipid accumulation and formation of lipid droplets, and also leads to mycobacterial lipid-activation of PPARγ." (PMID 31011554, 2019). "qRT‐PCR analysis revealed that lenti‐shZFP36L1 infection remarkably decreased ZFP36L1 mRNA expression which resulted in significant up‐regulation of the mRNA levels of the adipogenic differentiation markers (PPARγ, PLIN1, LPL and FABP4) as compared with the lenti‐control (lenti‐ctrl) infection." (PMID 29993187, 2018). "qRT‐PCR analysis revealed that lenti‐shPPARGC1B infection significantly decreased PPARGC1B mRNA expression, which resulted in significant down‐regulation of the mRNA levels of the adipogenic differentiation markers (PPARγ, PLIN1, LPL and FABP4) as compared with the lenti‐ctrl infection." (PMID 29993187, 2018). "We further investigated changes in protein expression of genes involved in lipid metabolism, and levels of three proteins (ACC1, PPARγ and FASN) were determined by western blotting on days 1 to 3 post infection after infection with DENV-4LAB and DENV-4DHF or mock infection." (PMID 28193229, 2017). "Together, these findings establish that activated PPARγ is sufficient to impair neuronal differentiation of NSCs, even without infection." (PMID 27078877, 2016). "Furthermore, the PPARγ agonist pioglitazone produced marked clinical improvement in a 5-month-old boy with CGD and multiple severe infections." (PMID 27774097, 2016). "To investigate whether infected NSCs could release soluble mediators able to trigger PPARγ expression, we purified the supernatants from infected or uninfected NSC cultures, 5 days post infection." (PMID 27078877, 2016). "In addition, PPARγ knock down resulted in enhanced viral replication as reflected by the HIV-p24 levels in supernatants at days 3 and 6 post-infection and the frequency of HIV-p24+ cells at day 7 post-infection." (PMID 24359430, 2013). "Evidence for a role of cholesterol in HIV-1 trans infection is that enhancing cholesterol efflux in DC by triggering of regulators of cholesterol metabolism, that is, peroxisome proliferator-activated receptor gamma and liver X receptor, decreases HIV-1 trans infection." (PMID 24278768, 2013). "PPAR activation and cPLA2 inhibition decreased significantly 6k-PGF1α, PGE1, and PGF1α production; however, PPARγ agonist was not able to reduce PGE2 production which increased significantly after infection (P < 0.001) at 60 and 120 min, respectively." (PMID 23555077, 2013). "Also, PPARγ signaling inhibits DC-mediated HIV capture and trans-infection at least in part by depleting cholesterol from the cell membrane." (PMID 24359430, 2013). "All these results may explain why, during PPARγ activation, PGE2 production increased during macrophages infection with L. mexicana." (PMID 23555077, 2013). "Our results show a more dramatic weight loss and more accentuated inflammatory lesions in tissue-specific PPARγ null mice following infection with C. difficile (data not shown)." (PMID 23071818, 2012). "Only when challenged with very high numbers of bacteria (100× LD50) this resistance to infection was broken and mice lacking PPARγ in myeloid cells then died even more rapidly than their wildtype littermates." (PMID 22629382, 2012). "In addition, we found that PPARγ and LXR ligand treatment of MDDCs prevented trans-infection over a wide range of input virus." (PMID 20617179, 2010).
infection (continued). "We did not see changes in the expression of PPARγ after infection." (PMID 36989308, 2023). "However, blocking the TLR2 signal with a neutralizing antibody (polyclonal anti-hTLR2 antibody, h-TLR2) against TLR2 before H37Ra infection did not promote the expression of PPARγ." (PMID 35432274, 2022). "The female mice exhibited higher expression levels of AKT1, BTK, CCL9, and LSP1 (KO, 1A0), PPARG (KO, 1A0, and 6A2), CFLAR, and ERP44 (1A0, 6A4), CCL9 (KO, 1A0, and 6A4), RCC2, and RELA (KO), KAT2B (6A2) and FKBP5 (1A0, 6A2, and 6A4) compared to males in response to infection." (PMID 32670284, 2020). "Infection of Schwann cells with recombinant M. bovis BCG that expresses a M. leprae phenolic glycolipid I (PGLI), important for bacterial entry into host cell induced expression of a PPARγ-dependent endocytic mannose receptor (MR/CD206) required for LD accumulation." (PMID 30991653, 2019). "In addition, infection increased the protein expression of FAS and PPARγ." (PMID 31604978, 2019). "This inhibition may reflect PPARγ-dependent reduction in neutrophils' ability to adhere to fibrinogen and to polymerize actin and/or suppression of ICAM-1 expression and contributes to the host's failure to contain infections." (PMID 27774097, 2016). "We found that positive macrophages to L. mexicana-induced oxidative burst increased from ~34.1 to 58.6% (P < 0.001) by PPARγ agonist at 120 min after infection compared to non-treated macrophages, whereas treatment with PPARβ/δ agonist increased from ~34.1 to 40.32% (P < 0.05)." (PMID 23555077, 2013). "However, RGZ significantly decreased HIV-DNA integration at late time points (day 14 post-infection) (data not shown), suggesting that PPARγ pathway activation limits HIV dissemination upon long-term treatment." (PMID 24359430, 2013). "However, unlike our previous results with Ad-DN-infected CASMCs, Ad-DN infection of PPARγ−/− ES did not induce cyclin A, MCM7, or pRb expression versus Ad-GFP-infected cells under either serum-starvation or -stimulation conditions." (PMID 20300579, 2009). "Besides, PPARγ, some of the critical enzymes involved in fatty acid biosynthesis, TAG biosynthesis, cholesterol esterification like Fasn, Dgat1, Dgat2, Mgat1, Acat1, Acat2, etc., showed a temporal increase in expression levels at the later time points post-infection." (PMID 41358489, 2025). "Another study regarding the Ad36 infection of hADSCs cells reported that infection might promote FA and TAG synthesis and subsequent LD formation by modulating phosphoinositide 3-kinase (PI3K)/protein kinase B (Akt)/ forkhead box O1 (FoxO1)/ PPARγ signaling pathway." (PMID 35883666, 2022). "However, in response to infection, male mice exhibited higher expression levels of CFLAR, and FKBP5 (KO, 1A3), AKT1, and CCL9 (1A3, 6A2), C1QC (6A2), LSP1 (1A3, 6A2, and 6A4), CKAP2, and KAT2B (KO), TACC2 (1A0), RCC2 (1A3, 6A2), PPARG (1A3, 6A4), and ERP44 (6A2) compared to females." (PMID 32670284, 2020). "Exposure of THP1 cells to the same lentiviral particles for different time points revealed that IRAK-M and PPARγ were induced 24 hours following infection and not earlier, suggesting that it was not an immediate-early effect but may affect macrophage responses at later stages of infection." (PMID 28118607, 2017). "Together these data suggest that, unlike PPARγ- and LXR-mediated inhibition of migration, the inhibition of trans-infection is independent of the maturation state of the DC." (PMID 20617179, 2010). "The quantification of HIV-DNA integration at early time points (day 3 post-infection) in cells treated with RGZ after HIV exposure did not reveal statistically significant differences, suggesting that PPARγ pathway activation limits HIV replication by interfering with viral transcription." (PMID 24359430, 2013).
infection (continued). "Since, like HIV-1, both EboV and MarV glycoproteins are known to require cholesterol for infection, whereas VSV-G does not, this suggested that PPARγ and LXR might be exerting their effects through the regulation of cellular cholesterol." (PMID 20617179, 2010). "Importantly, PPARγ and LXR signaling inhibited both immature and mature DC-mediated trans-infection by preventing the capture of HIV-1 by DCs independent of the viral envelope glycoprotein." (PMID 20617179, 2010).
cardiovascular disease (94 papers, 2008 to 2026). "Similar results were also observed in a previous study that reported that the G allele in PPARG Pro12Ala is an associate factor for cardiovascular diseases." (PMID 35265101, 2022). "The cardioprotective effect of PPARγ activation has been studied extensively over the years making them potential therapeutic targets in diseases associated with cardiovascular disorders." (PMID 28243251, 2017). "In addition to the PPARG gene–phenotype associations for T2DM and cardiovascular diseases, researchers have reported a PPARG SNP interaction with diet (fat intake), with a significant influence on bone mineral density (BMD)." (PMID 37047733, 2023). "Among them, PPARγ binds to PPARγ coactivator 1α (PGC1α) to form a complex that activates multiple transcription factors and regulates several metabolic processes associated with cardiovascular diseases." (PMID 34422028, 2021). "Furthermore, APOE, a protective protein for cardiovascular diseases, can interact with PPARγ to decrease cardiovascular disease risk." (PMID 31534622, 2019). "Though treatment with activators of PPARγ seems to have a favorable effect on the risk factors for cardiovascular disease, it also has adverse effects on the cardiovascular system which mitigates its beneficial effects thus limiting their widespread use in patients with cardiovascular risk." (PMID 28243251, 2017). "For instance, linoleic acid improves lipid profiles by promoting lipid metabolism through Peroxisome Proliferator-Activated Receptor Gamma (PPARγ) activation, lowering LDL levels, and increasing HDL levels, thereby reducing the risk of cardiovascular diseases." (PMID 40978487, 2025). "Telmisartan, an angiotensin II type I receptor inhibitor used to control blood pressure and treat cardiovascular diseases, is another example of a PPARγ partial agonist." (PMID 39199386, 2024). "Unfortunately, the oral administration of these molecules, which are able to strongly activate PPARγ, provoked unwanted side effects at the same time (weight gain, fluid retention, osteoporosis, cardiovascular diseases, and bladder cancer)." (PMID 39199386, 2024). "Activation of peroxisome proliferator–activated receptors (PPARs), including PPARα, PPARβ/δ, and PPARγ, has been shown to exert beneficial effects in cardiovascular diseases such as atherosclerosis and MI." (PMID 37018396, 2023). "For example, PPARα agonists, PPARγ agonists, and MR antagonists are all clinically approved and commonly used to treat patients with metabolic and/or cardiovascular diseases." (PMID 37018396, 2023). "Considering the accumulating evidence, PPARγ has emerged as one of the promising therapeutic targets for cardiovascular disease." (PMID 37147722, 2023). "Telmisartan, an angiotensin II receptor blocker that has unique peroxisome proliferator-activated-receptor-gamma-mediated effects on cardiovascular disease, has been shown to enhance endothelial function and limit neointimal hyperplasia." (PMID 34834171, 2021). "This review aims to discuss the role of PPARγ in the various cardiovascular diseases and summarize the current knowledge on PPARγ agonists from multiple clinical trials." (PMID 28243251, 2017). "PPARγ plays an important role in cardiovascular diseases but much research is still needed to establish its function in the cardiovascular system." (PMID 28243251, 2017). "PPARγ has typically been studied in metabolic and cardiovascular diseases, but is also an important anti-inflammatory regulator due to its down-regulation of NFκB." (PMID 28886148, 2017). "Peroxisome proliferator activated receptor γ (PPARγ) has been closely involved in the process of cardiovascular diseases." (PMID 27110236, 2016). "Pioglitazone (PIO), another PPARγ agonist, also displayed protective effects in the cardiovascular diseases." (PMID 27110236, 2016).
cardiovascular disease (continued). "Inhibition of PPARγ functions, specifically in the vascular endothelium or smooth muscle cells, also affects the development of cardiovascular disease." (PMID 26980943, 2016). "Lipid metabolism related to peroxisome proliferator-activated receptor γ (PPARγ) signaling was modified, with possible implications for foam cell formation and development of cardiovascular diseases." (PMID 23825649, 2013). "PPARγ has many activities, leading to complicated and even paradoxical effects on adipocyte biology, insulin action, cardiovascular disease, inflammation." (PMID 22919315, 2012). "Increasing plasma adiponectin level or increasing adiponectin sensitivity with the aid of PPARγ agonists has been proposed as a promising therapeutic strategy for patients with metabolic and/or cardiovascular disease." (PMID 21490806, 2011). "Notably, unlike the beneficial insulin sensitizing function in adipose tissue, the role of PPARγ in cardiovascular disease remains controversial." (PMID 38280036, 2024). "Notably, mRNAs for most genes associated with cardiovascular diseases (e.g., HSD3B2, PPARG, NLN and CEACAM1) were downregulated in the colons of HBP subjects." (PMID 36768972, 2023). "Currently, we do not have any direct evidence defining the exact role of PPARγ in cardiovascular disease, but strongly believe that the role of PPARγ is determined by cellular or disease contexts that might be influenced by many factors." (PMID 31735914, 2019). "The role of PPARγ in the development of cardiovascular disease is somewhat controversial." (PMID 31735914, 2019). "Coincidentally, PPARγ shows a pivotal role in multiple other cardiovascular disease states." (PMID 27293418, 2016). "Therefore, further efforts are needed to investigate whether MTMR7 can function in cardiovascular diseases via affecting PPARγ." (PMID 38529329, 2024). "For example, the forced expression or disruption of PPARγ has incompatible effects in terms of VSMC proliferation, cardiovascular disease progression, and the mediation of pro- or anti-inflammatory responses." (PMID 31735914, 2019). "Therefore, PPARγ is a potential therapeutic target for transcriptional regulation of VSMC proliferation and migration in cardiovascular diseases." (PMID 36293172, 2022).
neurodegenerative disease (83 papers, 2010 to 2025). A disorder of the central nervous system characterized by gradual and progressive loss of neural tissue and neurologic function. "The use of PPARγ antagonists in neurodegenerative diseases associated with inflammatory processes has recently been proposed." (PMID 36233271, 2022). "The involvement of PPARG in mitochondrial biogenesis and cell survival in neurons has been extensively implicated in neurodegenerative diseases." (PMID 36077049, 2022). "The evidence covered by this review indicates that PPARγ agonists act simultaneously on several cellular metabolism and repair processes in the CNS that become dysfunctional because of cellular damage caused by neuroinflammatory and neurodegenerative diseases." (PMID 36834611, 2023). "Recently, PPARγ has been implicated in macrophage polarization from M1, the classically activated phenotype, to M2, the alternatively activated phenotype, in several neurodegenerative diseases." (PMID 30420872, 2018). "In neurodegenerative diseases, including AD, PPARγ is being investigated for its neuroprotective potential." (PMID 40926269, 2025). "Further studies regarding the mechanistic differences between PPARγ stimulation of Aβ- and tau-related microglial activation will provide novel insights into the pathomechanisms of neurodegenerative diseases and possible new treatment strategies." (PMID 37373253, 2023). "Leriglitazone (LGZ) is an oral bioavailable selective PPARγ agonist that has an improved profile compared with other drugs acting on the same target for treating neurodegenerative diseases." (PMID 37884937, 2023). "Neuroprotective mechanisms involving PPARγ TZD in neurodegenerative diseases have been extensively studied in preclinical models." (PMID 36834611, 2023). "The involvement of PPARG in neuroprotection has been extensively documented in neurodegenerative diseases." (PMID 35370543, 2022). "Recent studies have revealed that PPARγ exerts anti-inflammatory functions and therefore improves brain injury or neurodegenerative diseases." (PMID 34744713, 2021). "Based on preclinical studies, PPARγ is involved in the etiology of neurodegenerative disease, and reduced PPARγ expression is related to the pathogenesis of AD." (PMID 34834468, 2021). "PPAR, which PPARG belongs to, is believed to be the therapeutic target of neurodegenerative diseases." (PMID 31608111, 2019). "The nuclear receptors (NRs) RARα, RXRα, PPARα, and PPARγ represent promising pharmacological targets for the treatment of neurodegenerative diseases." (PMID 30759808, 2019). "In the light of these findings, exploring the mechanisms of action of tideglusib (including GSK-3β inhibition and PPARγ activation) are important in terms of neurodegenerative diseases." (PMID 30965670, 2019). "Recent evidence highlights peroxisome proliferator-activated receptor γ (PPARγ) as a critical neuroprotective factor in neurodegenerative diseases." (PMID 30410641, 2018). "Owing to the anti-inflammatory and potentially neuroprotective effects of PPARγ, PPARγ agonists are increasingly being used for the treatment of neurodegenerative diseases." (PMID 29258184, 2017). "A powerful effect of pioglitazone, demonstrated not only in the MPTP model of PD but other neurodegenerative diseases as well, is the ability to reduce neuroinflammation mainly by activating PPARγ in microglia." (PMID 27038906, 2016). "PPARγ has been proposed as a therapeutic target against neurodegenerative diseases because of its anti-inflammatory action in glial cells." (PMID 25246934, 2014). "PPARγ agonist pioglitazone has been reported to have beneficial effects on neurodegenerative disease mouse models." (PMID 24495352, 2014).